GRK2 (G protein-coupled receptor kinase 2)
Diseases named in the same sentence as GRK2 in open-access papers (continued):
Sharing a sentence is not in itself a finding about the gene and the disease.
atherosclerosis (3 papers, 2013 to 2025). A disease characterized by the build-up of fatty material and calcium deposition in the arterial wall resulting in partial or complete occlusion of the arterial lumen. "Contrary to these findings, atherosclerosis is attenuated in mice with a haemopoietic deficiency in GRK2 +/−, that is accompanied by a 79% decrease in necrotic core size." (PMID 23690662, 2013). "Future research should investigate the potential crosstalk between vascular endothelial and myeloid cells involving GRK2 signaling, which could provide further insights into molecular mechanisms underlying atherosclerosis and lead to more effective treatment strategies." (PMID 40492401, 2025). "OSS increases the expression level of GRK2S29p, and the use of vascular endothelial cell‐specific GRK2 knockout mice and chemical GRK2 inhibitors further supports the potential of targeting GRK2 as a therapeutic strategy for atherosclerosis." (PMID 40492401, 2025). "Our results confirmed that vascular endothelial cell‐specific knockout of GRK2 reduces atherosclerosis in ApoE‐/‐ mice fed a high‐fat Western diet." (PMID 40492401, 2025). "Third, paroxetine, a GRK2 inhibitor, has protective effects against disturbed flow‐induced vascular endothelial dysfunction and atherosclerosis." (PMID 40492401, 2025). "Given the important role of GPCRs in mechanotransduction, targeting GRK2 may offer a novel therapeutic approach for atherosclerosis." (PMID 40492401, 2025). "Moreover, endothelial-selective GRK2 removal induces early atherosclerosis in the aortas and inhibits neoangiogenesis in mice." (PMID 29531822, 2018). "Notably, treatment with paroxetine, a chemical GRK2 inhibitor, significantly reduced OSS‐induced vascular endothelial dysfunction, suggesting that GRK2 could be a potential target for developing new drugs to treat atherosclerosis in the future." (PMID 40492401, 2025). "Notably, we constructed vascular endothelial cell‐specific GRK2 knockout mice on an ApoE‐/‐ background to investigate whether vascular endothelial cell‐specific knockout of GRK2 could alleviate the development of atherosclerosis." (PMID 40492401, 2025). "Understanding the GRK2/AP‐1/NR4A1 signaling axis in disturbed flow‐induced vascular endothelial dysfunction and atherosclerosis will aid in the development of novel drugs, offering more targeted and effective treatment options for vascular diseases." (PMID 40492401, 2025). "Our study highlights the pivotal role of GRK2 in mediating OSS‐induced vascular endothelial dysfunction and atherosclerosis." (PMID 40492401, 2025). "Taken together, our results indicate that GRK2 might be a treatment target for OSS‐induced vascular endothelial dysfunction and atherosclerosis." (PMID 40492401, 2025). "However, a conditional GRK2 deficiency in a macrophage/granulocyte specific transgenic model (LysM-Cre GRK2 flox/flox) did not display any differences in atherosclerosis indicating that macrophages were not solely responsible for the phenotype observed in GRK2+/− bone marrow chimeras." (PMID 23690662, 2013).
breast tumor (3 papers, 2019 to 2024). "The GRK2 gene undergoes amplification in specific human cancers, such as breast tumors and esophageal cancer, while protein upregulation is frequently observed in luminal breast tumors or pancreas cancer." (PMID 39198399, 2024). "Concurrently, GRK2 downregulation takes place in the breast tumor vessels." (PMID 32413989, 2020). "Therefore, we used the cell line MCF7, a model of estrogen receptor (ER)-positive and luminal A human breast tumors engineered to express different dosages of GRK2, and further characterized the effects on HuR." (PMID 32413989, 2020). "Therefore, GRK2-phosphorylated HuR might also directly modulate the VEGF-C mRNA in breast tumor MCF7 cells." (PMID 32413989, 2020). "First, does the GRK2/HDAC6 module promote changes in the acetylation status and activity of other players in breast tumor progression?" (PMID 31432234, 2019).
dilated cardiomyopathy (3 papers, 2018 to 2021). Cardiomyopathy which is characterized by dilation and contractile dysfunction of the left and right ventricles. "Moreover, cardiac-specific βARKct overexpression prevents cardiac remodeling and development of HF in MLP KO mice, a model of dilated cardiomyopathy with elevated GRK2 levels in the heart, suggesting that inhibition of GRK2 activity represents an approach to prevent the development of HF." (PMID 30538631, 2018).
fibrosis (3 papers, 2016 to 2023). the formation of excess fibrous connective tissue in an organ or tissue in a reparative or reactive process. "Previous studies have shown that increased GRK2 expression in pathological cardiac remodeling increases the expression of genes related to cardiac fibrosis, which is consistent with our results." (PMID 38139099, 2023).
leukemia (3 papers, 2015 to 2021). A malignant (clonal) hematologic disorder, involving hematopoietic stem cells and characterized by the presence of primitive or atypical myeloid or lymphoid cells in the bone marrow and the blood. "Moreover, miR-125b was reported to promote leukemia cell resistance to daunorubicin through inhibiting expression of G protein-coupled receptor kinase 2 and apoptosis." (PMID 25605244, 2015).
lymphoma (3 papers, 2016 to 2021). A malignant (clonal) proliferation of B- lymphocytes or T- lymphocytes which involves the lymph nodes, bone marrow and/or extranodal sites. "In addition to this newly described role in MALT1-dependent lymphoma, protein-protein interactions involving GRK2 have also been implicated as influencing the pathogenesis of the related B-cell malignancy, chronic lymphocytic leukemia (CLL)." (PMID 33546162, 2021). "Further investigation unveiled a potential function of GRK2 as an onco-modulator/tumor suppressor by blocking MALT1 activity in MALT1-dependent lymphomas." (PMID 33546162, 2021). "Examination of PEL cell lines showed the expression of GRK2 was in general lower in KSHV-positive PEL cells including BC3 and BCBL-1 cells than in KSHV-negative lymphoma cells including DG75, Loukes and BJAB cells." (PMID 27058419, 2016). "In lymphoma cells, knockout of GRK2 leads to enhanced MALT1-mediated IκB phosphorylation, RELB and CYLD cleavage, cytokine secretion, and cell proliferation, and GRK2 rescue reverses these effects." (PMID 34917606, 2021). "Lastly, precisely how GRK2 influences the functionality of its interaction partners in lymphocytes including TCR CD3ε, MALT1, RKIP, etc., are important questions whose answers will advance our understanding of normal immune response as well as the pathogenesis of lymphoid cancers." (PMID 33546162, 2021).
medulloblastoma (3 papers, 2019 to 2022). A malignant, invasive embryonal neoplasm arising from the cerebellum. "Here we report that GRK2 knockdown slowed cell growth, diminished proliferation, and enhanced cisplatin- and etoposide-induced apoptosis in medulloblastoma cell lines UW228-2 and Daoy." (PMID 31554835, 2019). "siGRK2 knockdown did not affect protein level of its closest family member, GRK3, strengthening our conclusion that GRK2 contributes to growth and proliferation of medulloblastoma cell lines UW228 and Daoy." (PMID 31554835, 2019). "Together, this is the first report of a growth-promoting function for GRK2 in medulloblastoma cells and its potential role in their response to chemotherapy." (PMID 31554835, 2019). "We found a medulloblastoma-promoting effect of GRK2 in two SHH subgroup medulloblastoma cell lines, UW228 and Daoy95–97." (PMID 31554835, 2019). "In summary, we identified GRK2 as a contributor to regulation of cell growth and survival in two medulloblastoma cell lines." (PMID 31554835, 2019). "We first examined the effect of GRK2 knockdown on growth of medulloblastoma cell lines UW228-2, Daoy and D283Med." (PMID 31554835, 2019). "In the present study we demonstrate for the first time a pro-survival role for GRK2 in two SHH subgroup medulloblastoma cell lines and GRK2-mediated mitigation of their cisplatin- and etoposide-induced apoptosis." (PMID 31554835, 2019). "We then asked if the protective effect of GRK2 in medulloblastoma cells extended to treatment with etoposide, another chemotherapy that is commonly used against medulloblastomas." (PMID 31554835, 2019). "This suggests that GRK2 may contribute to chemoresistance of medulloblastoma to cisplatin and etoposide via AKT." (PMID 31554835, 2019). "Considering the diverse signaling pathways affected by GRK2, it is possible that its action in medulloblastomas growth and protection from chemotherapy may be mediated via both Smoothened dependent and/or independent mechanisms." (PMID 31554835, 2019). "We therefore asked if GRK2 would protect medulloblastoma cells from cisplatin-induced apoptosis." (PMID 31554835, 2019). "Since GRK2 inhibitors being developed for cardiac protection are mostly focused on inhibiting kinase-dependent effects of GRK2, caution will be needed if they are considered for medulloblastoma." (PMID 31554835, 2019). "The role of GRK2 in SHH/Smoothened signaling in invertebrate development and in mammalian cells suggest a potential link to medulloblastoma." (PMID 31554835, 2019). "The work presented here provides evidence supporting a medulloblastoma-promoting effect of GRK2 by showing that decreasing GRK2 reduced growth and proliferation of UW228 and Daoy medulloblastoma cell lines." (PMID 31554835, 2019). "There is a trend towards shorter overall survival for patients with higher-than-median GRK2 mRNA in their medulloblastomas, but this difference is not statistically significant." (PMID 31554835, 2019). "These RNA data do not preclude a role for GRK2 in vivo in medulloblastomas, since GRK2 is also regulated at the protein level via proteasomal degradation." (PMID 31554835, 2019). "GRK2 can regulate SHH/SMO signaling at different points along their signaling pathway and is expressed in medulloblastomas, but to date, has not been implicated in medulloblastoma biology." (PMID 31554835, 2019). "Limited experiments in D283Med cells (Group 3 medulloblastoma) with GRK2 knockdown over a six-day culture period did not reveal differences compared to control cells." (PMID 31554835, 2019). "This suggests that GRK2-mediated protection of these medulloblastoma cells from cisplatin-induced apoptosis is at least partly independent of the kinase activity of GRK2 in a yet-unknown mechanism." (PMID 31554835, 2019). "GRK2 has not been characterized or targeted in GBM, but is known to promote tumorigenesis and chemotherapy-induced apoptosis in breast and medulloblastoma cells." (PMID 33806345, 2021).
osteoarthritis (3 papers, 2022 to 2023). A noninflammatory degenerative joint disease occurring chiefly in older persons, characterized by degeneration of the articular cartilage, hypertrophy of bone at the margins and changes in the synovial membrane. "We hypothesize that Gβγ-GRK2 signaling promotes the early inflammatory response and chondrocyte loss in osteoarthritis (OA)." (PMID 35887281, 2022).
pulmonary fibrosis (3 papers, 2020 to 2023). Chronic progressive interstitial lung disorder characterized by the replacement of the lung tissue by connective tissue, leading to progressive dyspnea, respiratory failure, or right heart failure. "Collectively, these data further unveiled that PRXT-mediated inhibition of GRK2 decreased the mRNA and protein expression of Smad3 during pulmonary fibrosis." (PMID 37815883, 2023). "Here, we also found that PRTX could inhibit GRK2 during pulmonary fibrosis, subsequently blocking the activation of TGF-β1/Smad3 pathway." (PMID 37815883, 2023). "One previous study has reported that GRK2 levels were increased in lungs and isolated fibroblast cells during pulmonary fibrosis and GRK2 inhibition could decrease extracellular matrix (ECM) accumulation by downregulating Smad3 expression." (PMID 37815883, 2023). "The beneficial effects of PRXT on pulmonary fibrosis may be attributed to its inhibition on GRK2 as well as Smad3 in lung fibroblasts." (PMID 37815883, 2023). "We also found that GRK2 inhibition by PRTX decreased oxidative stress level during pulmonary fibrosis, hinting that GRK2 may regulated the proteins responsible for redox biology." (PMID 37815883, 2023). "This study demonstrated that PRXT treatment could prevent bleomycin-induced pulmonary fibrosis in vivo and in vitro by regulating GRK2/Smad3 signaling pathway." (PMID 37815883, 2023). "Based on these findings, we hypothesized that PRXT could effectively protect against bleomycin-induced pulmonary fibrosis by decreasing oxidative stress and blocking the activation of lung fibroblasts through regulating GRK2." (PMID 37815883, 2023). "Nintedanib mediated a downregulation of chemokine (C-X-C motif) receptor 2 (CXCR2) and very late antigen 4 (VLA-4) expression, as well as an upregulation of G protein-coupled receptor kinase 2 (GRK2) activity in peripheral blood neutrophils in BLM-induced pulmonary fibrosis." (PMID 32630825, 2020). "Moreover, our study demonstrated that nintedanib downregulated Ly6G and CXCR2 expression levels in circulating neutrophils while upregulating GRK2 expression in pulmonary fibrosis." (PMID 32630825, 2020). "In conclusion, PRXT mediates the inhibition of GRK2, which further blocks the transcription of Smad3 in TGF-β1-induced lung fibroblasts, providing an attractive therapeutic target for pulmonary fibrosis." (PMID 37815883, 2023). "GRK2 promoted TGFβ1-induced ECM accumulation by transcriptionally activating Smad3 in lung fibroblasts, the inhibition of which thus attenuated bleomycin-induced lung fibrosis." (PMID 37815883, 2023). "G protein-coupled receptor kinase-2 (GRK2) is involved in TGF-β1-induced activation of lung fibroblasts, which could give rise to the pathogenesis of pulmonary fibrosis." (PMID 37815883, 2023). "Although GRK2 has been confirmed to be involved in the development of pulmonary fibrosis by regulating multiple signaling pathways, the exact role of GRK2 has not yet been clearly illustrated." (PMID 35111168, 2021). "However, the decreased GRK2 is shown in the development of pulmonary fibrosis, and there is another result indicates that desensitization of A2AR by GRK2 may contribute to down-regulating the process of liver fibrosis." (PMID 35111168, 2021).
thyroid cancer (3 papers, 2013 to 2020). "Altogether these findings are of great interest in the cancer field for the identification of a novel strategy to reduce thyroid cancer progression mediated by the inhibition of GRK2 activity." (PMID 33256128, 2020). "Here, we show that this ability of GRK2 is also retained in thyroid cancer, where it is highly active." (PMID 33256128, 2020). "Furthermore, increased GRK2 expression and activity were detected in thyroid cancer, but its effects and mechanisms of action were not investigated yet." (PMID 33256128, 2020).
age (2 papers, 2013 to 2024). A temporal measurement of the time period elapsed since an identifiable point in the life cycle of an organism. "At vascular level, exercise shows a therapeutic effect on age-related impairment of vascular reactivity to adrenergic stimulation and restores β-AR-dependent vasodilatation by increasing vascular β-AR responsiveness and reducing endothelial GRK2 activity." (PMID 24348425, 2013).
allergic asthma (2 papers, 2021 to 2022). A asthma with a basis in a pathological type I hypersensitivity reaction. "For example, GRK2 is upregulated in human asthmatic lungs, it associates with T cell receptors, and T-cell-specific deletion of GRK2 attenuates airway inflammation and hyperresponsiveness in mouse model of allergic asthma." (PMID 36275707, 2022). "We have previously shown that GRK2 regulated mast cell responses to the C3a and the IgE receptors, which play an important role in mediating allergic asthma in humans." (PMID 35386975, 2021). "Thus, the prospect of using paroxetine based GRK2 inhibitors against allergic asthma is an attractive possibility." (PMID 36275707, 2022). "Additionally, T-cell-specific GRK2 promotes the pathogenesis of allergic asthma in a mouse model." (PMID 36275707, 2022). "Although not related to the desensitization function of GRK2, patients with allergic asthma (likely MC-mediated) exhibit GRK2 levels that are enhanced in the lungs compared to healthy controls." (PMID 36275707, 2022).
allergic reactions (2 papers, 2022 to 2024). "In contrast to its function in GPCR desensitization, GRK2 promotes IgE/FcεRI mediated MC signaling, which is well-documented in the development and progression of several MC-mediated allergic diseases and hypersensitive reaction." (PMID 36275707, 2022). "In summary, we demonstrated that paroxetine and a related GRK2 inhibitor not only have an attractive clinical prospect in targeting allergic reactions, but also may serve to enhance host defense via MRGPRX2/MRGPRB2 activation." (PMID 36275707, 2022).
anaphylaxis (2 papers, 2023 to 2024). An acute hypersensitivity reaction that occurs from exposure to an allergen. "Deletion of Grk2 in MCs attenuated IgE-mediated passive cutaneous anaphylaxis (PCA) and itch but not passive systemic anaphylaxis (PSA)." (PMID 37063868, 2023). "In this study, we demonstrated that while GRK2 promotes IgE-mediated calcium mobilization and degranulation in PLMCs in vitro via the tyrosine phosphorylation of STAT5, it promotes local cutaneous anaphylaxis but not systemic anaphylaxis." (PMID 37063868, 2023).
cardiomyopathies (2 papers, 2016 to 2020). "In such scenario, GRK2 upregulation would be a relatively early event in the development of the metabolically-induced cardiomyopathy, as has recently been suggested, and as is the case for other cardiac conditions in which GRK2 levels increase in the first stages of the heart disease." (PMID 27832814, 2016). "However, expression of GRK2 and other biomarkers mentioned previously are not exclusive for the DCM, and high levels of biomarkers have also been found in other different cardiomyopathies and stress." (PMID 31680450, 2020).